CIBAR1 (CBY1 interacting BAR domain containing 1)
Description:
Plays a critical role in regulating mitochondrial ultrastructure and function by maintaining the integrity of mitochondrial morphology, particularly the organization of cristae. Preferentially binds to negatively charged phospholipids like cardiolipin and phosphatidylinositol 4,5-bisphosphate enhancing its interaction with mitochondrial membranes. Induces membrane curvature and tubulation, which are critical for maintaining mitochondrial ultrastructure and the organization of cristae. Plays a crucial role in ciliogenesis. May play a role in limb development through its role in ciliogenesis. Plays a key role in the correct positioning of the annulus, a septin-based ring structure in the sperm flagellum, serving both as a physical barrier and a membrane diffusion barrier that separates the midpiece (MP) from the principal piece (PP) (By similarity). This positioning is essential for proper sperm motility and function (By similarity). Interacts with CBY3 to form a complex which localizes to the curved membrane region of the flagellar pocket (By similarity). By doing so, may provide stability and rigidity to the periannular membrane to prevent membrane deformation (By similarity). This function is crucial for halting annulus migration at the proximal end of the fibrous sheath-containing PP (By similarity).
Synonyms: FAM92A; FAM92A1; FLJ38979; BARMR1; PAPA9
Tractability: Antibody: UniProt places it where antibodies can reach, with high confidence. PROTAC: ubiquitination databases record sites on it.
Gene: Protein-coding gene on chromosome 8 (93,698,561 to 93,731,527, forward strand). Ensembl gene ENSG00000188343.
Subcellular location: Cytoplasm; Cytoplasm, cytoskeleton, microtubule organizing center, centrosome, centriole; Cytoplasm, cytoskeleton, cilium basal body; Cell projection, cilium; Nucleus; Mitochondrion inner membrane; Cell projection, cilium, flagellum; Nucleus (Isoform 3)
Subcellular location (Human Protein Atlas): Mitochondria
Gene Ontology:
Molecular function: phospholipid binding; protein binding
Biological process: cilium assembly; inner mitochondrial membrane organization; limb morphogenesis; membrane organization; membrane tubulation; positive regulation of smoothened signaling pathway; spermatogenesis
Cellular component: centriole; ciliary base; cytoplasm; mitochondrial crista; mitochondrial inner membrane; mitochondrion; nucleus; ciliary basal body; ciliary transition zone; sperm annulus; cilium; microtubule organizing center; motile cilium
Genetic constraint (gnomAD): Loss-of-function variants: 15 observed, 21.81 expected, observed/expected ratio (o/e) 0.69, 90% interval 0.46 to 1.06. The upper end of that interval is the gene's LOEUF score, 1.06, which puts it in group 4 of 6, group 1 being the genes least tolerant of losing a copy. Missense variants: 181 observed, 209.57 expected, observed/expected ratio (o/e) 0.86, 90% interval 0.76 to 0.98. Synonymous variants: 74 observed, 78.87 expected, observed/expected ratio (o/e) 0.94, 90% interval 0.78 to 1.14.
Homologues: Orthologues: chimpanzee CIBAR1 (99% identical), macaque CIBAR1 (96% identical), rabbit CIBAR1 (89% identical), dog CIBAR1 (87% identical), mouse Cibar1 (87% identical), rat Cibar1 (84% identical), guinea pig CIBAR1 (84% identical), tropical clawed frog cibar1 (68% identical), zebrafish cibar1 (66% identical), Drosophila melanogaster Fam92 (30% identical). Paralogues in human: CIBAR2 (42% identical).
Diseases named in the same sentence as CIBAR1 in open-access papers:
CIBAR1 is named in the same sentence as 18 diseases in open-access papers, as found by Europe PMC text mining. Sharing a sentence is not in itself a finding about the gene and the disease. The quoted sentences say what the papers report.
ciliopathy (2 papers, 2024 to 2025). A genetic disorder of the cellular cilia or the cilia anchoring structures, the basal bodies, or of ciliary function. "In this study, we have characterized ciliopathy phenotypes of ciBAR1-KO mice and found that loss of ciBAR1 results in left–right laterality defects, exocrine pancreatic degeneration, and altered glucose metabolism because of defective primary cilia." (PMID 39622622, 2025). "Consistent with its critical role in ciliogenesis, ciBAR1 has been previously implicated in non-syndromic postaxial polydactyly, a common feature of ciliopathies." (PMID 39622622, 2025). "ciBAR1-KO mice exhibit ciliopathy phenotypes such as embryonic lethality and exocrine and endocrine pancreatic defects, indicating that ciBAR1 plays a critical role in ciliogenesis in vivo." (PMID 39622622, 2025). "To investigate whether ciBAR1-KO mice show any ciliopathy phenotypes, we performed histological analyses of both kidneys and pancreata from adult mice." (PMID 39622622, 2025).
situs inversus (1 paper, 2025). A congenital condition in which there is complete right-to-left reversal of the position of the major thoracic and abdominal organs (that is, they are arranged in a mirror image of the normal positioning). "We did not observe any laterality defects such as situs inversus and heterotaxy in ciBAR1-KO postnatal and 2–7-mo-old mice, indicating that ciBAR1-KO embryos that exhibit abnormal left–right asymmetry die before birth." (PMID 39622622, 2025).
cancer (3 papers, 2019 to 2023). A tumor composed of atypical neoplastic, often pleomorphic cells that invade other tissues. "The CIBAR1, CLIC4, OGN, and ZNF483 are protein-coding genes, but nothing is known about their association with PCa and cancer in general." (PMID 37298233, 2023).
CIBAR1 also shares sentences with these, for which no sentence is quoted: acute myeloid leukemia (1 paper); Alzheimer disease (1); autism (1); CNS cancer (1); cognitive deficits (1); dementia (1); glioma (1); lipomatosis (1); male infertility (1); malignant glioma (1); neurological disorders (1); osteosarcoma (1); polydactyly (1); Renal cyst (1); ventricular dilatation (1).